FAT1 (FAT atypical cadherin 1)
Diseases named in the same sentence as FAT1 in open-access papers (continued):
Sharing a sentence is not in itself a finding about the gene and the disease.
pancreatic cancer (9 papers, 2012 to 2024). "An expression analysis of isoforms of glypicans in pancreatic cancer cells followed by co-IP analysis might reveal whether GPC-FAT1 interaction is necessary for causing conformation changes that might facilitate extracellular FAT1 cleavage." (PMID 33878524, 2021). "In the present report we describe the release of high levels of the ectodomain of the giant Fat1 cadherin into the secretomes of human pancreatic cancer cells in vitro, a process that is also recapitulated in the serum of patients with pancreatic cancer." (PMID 24625754, 2014). "Collectively these results prompted us to further investigate the mechanisms underpinning the release of Fat1 from pancreatic cancer cells and its potential as a serum biomarker of pancreatic cancer." (PMID 24625754, 2014). "Here, we present the first description of a soluble isoform of Fat1 released from pancreatic cancer cells in vitro." (PMID 24625754, 2014). "In the present study we found increased expression of Fat1 mRNA in pancreatic cancer over normal controls in five large microarray data sets." (PMID 24625754, 2014). "Quite remarkably we have estimated the amount of Fat1 in the pancreatic cancer secretome to represent at least 1‰ of the total protein content as determined by quantitative MS using the AQUA method." (PMID 24625754, 2014). "In the present report we describe the release of high levels of the ectodomain of Fat1 cadherin into the secretomes of human pancreatic cancer cells in vitro, a process that is mediated by ADAM10." (PMID 24625754, 2014). "Fat1 and its sheddase ADAM10 are overexpressed in pancreatic adenocarcinomas and ectodomain shedding is also recapitulated in vivo leading to increased Fat1 serum levels in some pancreatic cancer patients." (PMID 24625754, 2014). "The apparent molecular range (Mr) of the Fat1 band in pancreatic cancer secretomes is in the range of the predicted Mr of the full-length core Fat1 polypeptide of 505 kDa." (PMID 24625754, 2014). "We also confirmed that Fat1 protein levels were similarly increased in pancreatic cancer relative to adjacent normal pancreatic tissue." (PMID 24625754, 2014). "Fat1 expression and proteolytic processing was analyzed by mass spectrometry and Western blotting using pancreatic cancer cell lines as compared to human pancreatic ductal epithelial cells." (PMID 24625754, 2014). "Using the whole-exome sequencing approach, non-synonymous mutations of human FAT1, FAT3 and FAT4 genes are detected in 1 each, and 2 out of 24 pancreatic cancer samples, respectively." (PMID 23076869, 2012). "Interestingly, in pancreatic cancer FAT1 was shown to be overexpressed on the surface of cancer cells together with ADAM10 metalloprotease, which mediates FAT1 ectodomain shedding." (PMID 30416985, 2018). "Fat1 cadherin is a major component of the secretome of pancreatic cancer cell lines." (PMID 24625754, 2014). "Since the band intensities in the secretomes correlated with the peptide counts determined for each respective cell line, taken together these data provide good evidence that Fat1 is highly abundant in the secretomes of pancreatic cancer cell lines but less so in their normal cellular counterparts." (PMID 24625754, 2014). "Furthermore in all cohorts there was also a significant increase in the levels of the ADAM10 sheddase in pancreatic cancer, an association that may have pathophysiological significance since we demonstrated that this particular metalloprotease was involved in ectodomain shedding of Fat1 in vitro." (PMID 24625754, 2014). "Therefore, we next determined whether the in vitro observation of increased Fat1 in secretome also translated into detectable Fat1 protein in the sera of pancreatic cancer patients." (PMID 24625754, 2014).
pancreatic cancer (continued). "Therefore the overexpression of Fat1 in concert with the apparent overexpression of the enzyme largely responsible for its cleavage (ADAM10) appears to provide some explanation for the abundance of the Fat1 protein in pancreatic cancer cell secretomes." (PMID 24625754, 2014). "We then compared the ability to detect Fat1 in the serum of pancreatic cancer patients to that of the biomarker CA19-9, the only serum marker in clinical use for monitoring pancreatic cancer patients." (PMID 24625754, 2014). "In light of the fact that significant overexpression of Fat1 and of its sheddase ADAM10 appears to be common in human pancreatic cancer it came as a surprise that the subpopulation of patients with increased levels of soluble Fat1 is restricted." (PMID 24625754, 2014). "Similarly, in pancreatic cancer cases [pancreatic adenocarcinoma (PAAD); n = 179], FAT1 expression correlated inversely with infiltration of monocytes, CD8+ T cells, CD4+ T cells, and dendritic cells, while it correlated positively with that of MDSCs." (PMID 35720420, 2022). "Neither Fat1 nor any other mammalian Fat cadherin has previously been investigated in studies of pancreatic cancer or adult pancreatic tissues." (PMID 24625754, 2014). "Fat1 has not previously been investigated in pancreatic cancer." (PMID 24625754, 2014). "Using a centrifugation protocol to enrich for very large proteins and protein complexes, a Fat1 immunoreactive band could be identified in the serum of two out of 11 patients with pancreatic cancer but was absent in all normal control sera examined (n = 10)." (PMID 24625754, 2014).
acute lymphoblastic leukemia (8 papers, 2012 to 2025). Leukemia with an acute onset, characterized by the presence of lymphoblasts in the bone marrow and the peripheral blood. "FAT1, originally cloned from the T-cell acute lymphoblastic leukemia (T-ALL) cell line Jurkat4, is mutated in 12–16% of T-ALL patients." (PMID 36653435, 2023). "FAT1 mRNA expression is upregulated in 11% of acute myeloid leukemia (AML), 29% of preB acute lymphoblastic leukemia (ALL) and 63% of T-ALL, and FAT1 upregulation in preB-ALL is associated with shorter relapse-free survival as well as shorter overall survival." (PMID 23076869, 2012). "Although its role in tumorigenesis is still controversial, in some cancers such as acute myeloid leukemia (AML), pre-B acute lymphoblastic leukemia (ALL), T-ALL, and hepatocarcinoma, FAT1 has been described to act as tumor promoter." (PMID 30416985, 2018).
colon carcinoma (8 papers, 2015 to 2022). "The specificity of the FAT1 recognition in colon cancer was confirmed by pre-adsorbing mAb198.3, adsorption dramatically abolished the antibody reactivity on colon cancer, thus confirming the binding specificity." (PMID 26373379, 2015). "Notably, we observed that mutations in KRAS, PIK3CA, CREBBP, FAT1, PKHD1, ARID2, and POLE were specifically enriched in right-site colon cancers in both our cohort and the validation cohort." (PMID 36439454, 2022). "Interestingly, the same authors provided evidence of an ADAM10-dependent FAT1 shedding in HCT15 colon carcinoma cell line, as demonstrated by the accumulation of FAT1 on the cell surface upon siRNA-mediated silencing of ADAM10 mRNA." (PMID 30416985, 2018). "Here we show that several murine cancer cell lines, including the colon cancer cell line CT26, expose FAT1 on their surface." (PMID 30416985, 2018). "FAT1-specific mRNA was present in all cancer cells and, interestingly, FAT1 mRNA was particularly abundant in CT26 cell line, a colon cancer cell line derived from BALB/c mice." (PMID 30416985, 2018). "One of us and his group have validated a tumorigenesis inhibiting effect in the Fat-1 mouse model with endogenously increased omega-3 PUFA for liver cancer and colon cancer; this fits well with data from other groups employing the Fat-1 mouse model." (PMID 26301240, 2015).
Nephropathy (8 papers, 2016 to 2023). A nonspecific term referring to disease or damage of the kidneys. "Loss of the cadherin FAT1 has been associated with nephropathy and epithelial cell adhesion defects." (PMID 30862798, 2019). "Loss of FAT1 function causes decreased epithelial cell adhesion and podocyte foot process effacement, resulting in abnormal glomerular filtration and nephropathy in humans and mouse, and cystic kidney in zebrafish." (PMID 30862798, 2019). "Here we show that recessive mutations in FAT1 cause a distinct renal disease entity in four families with a combination of SRNS, tubular ectasia, haematuria and facultative neurological involvement." (PMID 26905694, 2016). "In case 2, colobomatous-microphthalmia, ptosis, nephropathy and limb malformation correspond dramatically to what is described in the few patients with FAT1 homozygous frameshift variants reported so far, and strengthen the role of the novel variant we have identified." (PMID 34202629, 2021). "The second sister, case 2, presents a malformative picture that is largely similar to the one reported for homozygous frameshift mutations in the FAT1 gene, including colobomatous microphthalmia, ptosis, nephropathy and toe syndactyly, but also polydactyly of hand and foot and split foot." (PMID 34202629, 2021). "For example, the discovery of an association between variation in FAT1 and a human phenotype of steroid-resistant nephropathy with neurologic involvement benefitted from studies in zebrafish and mice, demonstrating that loss of Fat1 leads to abnormal podocyte and brain development." (PMID 28874452, 2017). "However, in the glomerulotubular disease described here renal disease resulting from FAT1 mutations is recessive, requiring two mutant alleles, which are inherited from the heterozygous parents." (PMID 26905694, 2016). "Fat-1 transgene can efficiently protect against kidney fibrosis in mice with UUO nephropathy." (PMID 28393852, 2017). "To further explore the signaling pathways which may be related to the protective effect for fat-1 transgene in kidneys with UUO nephropathy, we examined mTOR and Smad signaling pathways in kidney tissue from various groups." (PMID 28393852, 2017). "Furthermore, knockdown of fat1 in zebrafish causes formation of pronephric cysts, which is partially rescued by RAC1/CDC42 activators, confirming a role of the two small GTPases in the pathogenesis of this renal disease." (PMID 26905694, 2016). "Mechanistic insights into the FAT1-mediated regulation of SMC activities, including mitochondrial function and cell metabolism, may extend beyond cardiovascular biology to impact other areas of great importance for human health, notably renal disease and cancer biology." (PMID 35647082, 2022).
lung adenocarcinoma (7 papers, 2020 to 2025). A carcinoma that arises from the lung and is characterized by the presence of malignant glandular epithelial cells. "FAT atypical cadherin 1 (FAT1) is a receptor-like protein with a high frequency of mutations in lung adenocarcinoma." (PMID 38453442, 2024). "The mRNA expression levels of the FAT1 gene in lung adenocarcinoma tissues were analyzed, along with its association with the prognosis of lung adenocarcinoma patients." (PMID 38453442, 2024). "TCGA database data revealed significantly higher FAT1 mRNA expression in lung adenocarcinoma tissues compared to adjacent lung tissues." (PMID 38453442, 2024). "FAT1 mutations, which occurred more frequently in lung squamous cell carcinoma (LUSC) compared with lung adenocarcinoma (LUAD), were under greater positive selection before WGD occurrence in LUSC." (PMID 39738653, 2024).
metastatic tumors (7 papers, 2019 to 2025). "However, gene analysis showed that only 6% of ER+/HER2− ABC harbored FAT1 loss-of-function mutations in their metastatic tumors after treatment with CDK4/6i, likely representing a small population of patients with resistance to CDK4/6i, and the predictive value FAT1 mutations remain unclear." (PMID 34771560, 2021). "For metastatic tumors from GENIE, a total of sixteen candidate genes had significantly higher SNV frequencies in MMR-d tumors, of which six genes (KMT2D (33.3%), JAK1 (28.3%), FAT1 (21.7%), ERBB4 (20.0%), KMT2A (20.0%), and MGA (20.0%)) had a SNV frequency ≥ 20% in MMR-d tumors." (PMID 36675550, 2023).
oral squamous cell carcinoma (7 papers, 2016 to 2024). "In addition, frequent inactivation of FAT1 due to mutations or deletions in humans is associated with esophageal squamous cell carcinoma, oral squamous cell carcinoma, astrocytoma, glioblastoma, colorectal cancer, and head and neck cancer." (PMID 35647082, 2022). "Similarly, FAT1 is expressed in oral squamous cell carcinomas and shows a diffuse cytoplasmic and nuclear pattern in poorly differentiated tumors." (PMID 35647082, 2022). "However, the functions of FAT1 are ambiguous in tumorigenesis owing to inconsistent research in oral squamous cell carcinoma (OSCC)." (PMID 35646625, 2022). "Despite implication of FAT1 in several malignancies, its role in oral squamous cell carcinoma (OSCC) remains unclear." (PMID 31783581, 2019).
lymphoma (6 papers, 2021 to 2024). A malignant (clonal) proliferation of B- lymphocytes or T- lymphocytes which involves the lymph nodes, bone marrow and/or extranodal sites. "Emerging evidence shows that FAT atypical cadherin 1 (FAT1) mutations occur in lymphoma and are associated with poorer overall survival." (PMID 38782965, 2024). "Although described as a tumor suppressor in various cancers, FAT1 was few found mutated in lymphoma entities to date." (PMID 35359413, 2022). "Recently, it has been reported that FAT1 mutations occur in lymphoma." (PMID 38782965, 2024). "Considering that DLBCL is the category of lymphoma with the highest incidence rate, this study aims to explore the role of FAT1 in DLBCL." (PMID 38782965, 2024). "Considering that diffuse large B cell lymphoma (DLBCL) is the category of lymphoma with the highest incidence rate, this study aims to explore the role of FAT1 in DLBCL." (PMID 38782965, 2024). "These two studies suggest that FAT1 plays a vital role in lymphoma." (PMID 38782965, 2024). "Therefore, we assume that FAT1 may affect the proliferation of DLBCL by regulating YAP1 in this form of lymphoma." (PMID 38782965, 2024). "However, the specific role of FAT1 in lymphoma remains unclear." (PMID 38782965, 2024). "The findings of this study therefore indicate that FAT1 exerts anti-tumor effects in DLBCL and may represent a novel target in the treatment of this form of lymphoma." (PMID 38782965, 2024).
prostate carcinoma (6 papers, 2011 to 2022). A carcinoma that arises from epithelial cells of the prostate gland. "Our previous studies have shown that introduction of the fat-1 gene into a prostate specific Pten knock-out mouse model of prostate cancer reduced tumor growth similar to the effect of an n-3 PUFA diet." (PMID 21655218, 2011). "In human prostate cancer cell lines transfected with the fat-1 gene, proliferation was inhibited through a reduction in GSK-3β phosphorylation and a subsequent downregulation of β-catenin and cyclin D1." (PMID 21655218, 2011). "Depletion of FAT1 reversed the suppression of cell proliferation and EMT resulting from S100A14 overexpression in prostate cancer." (PMID 35965328, 2022). "FAT1 is a tumor suppressor gene that affects the WNT signaling pathway and TMPRSS2 is an AR-regulated gene that is involved in a gene fusion (TMPRSS2-ERG) in prostate cancer." (PMID 31434336, 2019).
bladder cancer (5 papers, 2014 to 2024). "In addition to identifying CDKN1A mutations, we have highlighted inactivating FAT1 mutations as possible bladder cancer drivers, on the basis of protein-truncating mutations and deletions in our own and TCGA data." (PMID 24777035, 2014). "The most frequently mutated genes in ordinary bladder cancer are TP53x, KMT2A, SPTAN1, ERBB2, CREBBP, FAT1, ATM, and KMT2C." (PMID 36779496, 2023). "Additionally, the most frequently mutated genes in ordinary bladder cancer are KMT2C, ATM, FAT1, CREBBP, ERBB2, SPTAN1, and KMT2A." (PMID 39399176, 2024). "Furthermore, FAT1 knockdown inhibits, while FAT1 overexpression enhances, cell migration and invasion in gastric or bladder cancer cell lines." (PMID 37371091, 2023). "Although testing of FAT1 was impractical in our replication samples owing to moderate DNA quantity and the large size of the FAT1 gene, we performed in silico replication using publicly available data from 99 bladder cancers in the TCGA consortium." (PMID 24777035, 2014).
Facioscapulohumeral dystrophy (5 papers, 2013 to 2023). Facioscapulohumeral muscular dystrophy (FSHD) is characterized by progressive muscle weakness with focal involvement of the facial, shoulder and limb muscles. "Variants in FAT1 have further been identified in various other disorders, including multiple cancer types and patients with facioscapulohumeral dystrophy-like phenotype." (PMID 33418956, 2021). "Muscle phenotypes caused by disruption of Fat1 functions are highly regionalized, and the topography is reminiscent of the map of muscles undergoing degeneration in facioscapulohumeral dystrophy (FSHD)." (PMID 29768404, 2018). "This link is nicely illustrated by our recent findings showing that alterations of Fat1 are associated with Facioscapulohumeral dystrophy (FSHD)." (PMID 26393505, 2015). "Thus, FAT1 is an important factor for skeletal muscle formation, fulfilling complementary roles in different cell types, and the loss of FAT1 function seems to be relevant to pathologies of the skeletal muscle such as facioscapulohumeral dystrophy." (PMID 37371091, 2023). "Strikingly, the topography of muscle abnormalities caused by Fat1 loss-of-function resembles that of human patients with facioscapulohumeral dystrophy (FSHD)." (PMID 23785297, 2013).
hepatic steatosis (5 papers, 2016 to 2025). Steatosis is a term used to denote lipid accumulation within hepatocytes. "Different transgenic animal models overexpressing the Fat-1 gene have been developed to study the relationship between endogenous n-3 fatty acids and various diseases such as fatty liver, atherosclerosis, arthritis, and tumors." (PMID 40052160, 2025). "Although fenofibrate can also reduce blood lipids and improve fatty liver, it is less effective than Fat-1 in improving HDL-C levels and NEFA levels, as well as optimizing plasma apolipoprotein levels and lipoprotein distribution." (PMID 40052160, 2025). "While both models exhibited a reduction in the ω-6/ω-3 ratio, ω-3 PUFA supplementation led to a greater improvement of hepatic steatosis and inflammatory lipid mediator profile, compared with endogenous production in Fat-1 mice." (PMID 36778746, 2023). "To better investigate whether the expression of Fat-1 will exert a beneficial function in dyslipidemia and metabolic dysfunction-associated fatty liver disease (MAFLD), we established an adeno-associated virus 9 expressing Fat-1." (PMID 40052160, 2025). "Furthermore, endogenously high levels of n-3 PUFAs alleviate ethanol-induced liver steatosis in fat-1 transgenic mice." (PMID 38791514, 2024). "Moreover, tissue n-3 PUFAs protected against acute ethanol-induced hepatic steatosis and diet-induced fatty liver disease in fat-1 transgenic mice, through activation of cholesterol catabolism to bile acid and downregulation of hepatic inflammatory response." (PMID 27679638, 2016). "When conducting a head-to-head comparison between Fat-1 and fenofibrate, we found that both Fat-1 and fenofibrate effectively ameliorated HFD-induced hyperlipidemia and fatty liver in WT hamsters." (PMID 40052160, 2025). "Acute ethanol-induced hepatic steatosis was alleviated, and the hepatic expression of SREBP-1c and plasma levels of TNF-α, IL-6, and MCP-1 were reduced in fat-1 transgenic mice." (PMID 38791514, 2024). "Although Fat-1 reduced basal plasma TG and TC levels, CD-fed WT hamsters did not have hepatic steatosis." (PMID 40052160, 2025).